CARM1 (coactivator associated arginine methyltransferase 1)
Diseases named in the same sentence as CARM1 in open-access papers (continued):
Sharing a sentence is not in itself a finding about the gene and the disease.
breast carcinoma (continued). "Alteration of CARM1, mostly upregulation, was frequently reported in various types of human cancers, including breast cancer, prostate cancer and colorectal cancer, which appears to promote cancer initiation, progression and metastasis." (PMID 32487779, 2020). "Particularly, CARM1 function in breast cancer is, at least partially, mediated through its methyltransferase activity targeting a large number of proteins." (PMID 32206101, 2020). "Requirement of CARM1 for cell proliferation was also observed in two other ERα-positive breast cancer cell lines." (PMID 32206101, 2020). "In consistent with its critical role in estrogen/ERα-induced gene transcriptional activation, CARM1 was found to promote cell proliferation of ERα-positive MCF7 breast cancer cells in vitro and tumor growth in mice." (PMID 32206101, 2020). "In consistent with its critical role in estrogen/ERα-induced gene transcriptional activation, CARM1 was found to promote cell proliferation of ERα-positive breast cancer cells in vitro and tumor growth in mice." (PMID 32206101, 2020). "Here we focused on investigating PRMT4 (also called coactivator associated arginine methyltransferase 1, CARM1) in ERα-positive breast cancers due to its high expression and the associated poor prognosis." (PMID 32206101, 2020). "We focused on studying the function of CARM1 in ERα-positive breast cancer in the current study, as which accounts for around 70% of all breast cancer patients." (PMID 32206101, 2020). "In consistent with the observation that it plays a prominent role in estrogen/ERα-induced gene transcriptional activation, CARM1 was demonstrated to be required for ERα-positive breast cancer cell growth and tumorigenesis." (PMID 32206101, 2020). "Among all cancer types, the role of CARM1 in breast cancer, particularly in ER-positive breast cancer, was most studied 18, 25, 27, 29, 30, 33, 36-43." (PMID 32206101, 2020). "Conclusions: our study uncovered a “hypermethylation” strategy utilized by enhancer-bound CARM1 in gene transcriptional regulation, and suggested that CARM1 can server as a therapeutic target for breast cancer treatment." (PMID 32206101, 2020). "In the current study, employing genomic and transcriptomic approaches, we uncovered the chromatin-binding landscape and transcriptional targets of CARM1 in the presence of estrogen in ERα-positive breast cancer cells." (PMID 32206101, 2020). "Taken together, our data suggested that CARM1 is required for ERα-positive breast cancer cell growth and tumorigenesis, exemplified by MCF7 cells." (PMID 32206101, 2020). "In the current study, utilizing MCF7 cells as a model system, we focused on investigating CARM1 function in ERα-positive breast cancers." (PMID 32206101, 2020). "Our scRNA-seq analysis provides the unprecedented insight that pharmacological inhibition of CARM1 alters epigenetic plasticity and suppresses invasion by suppressing the most invasive subpopulation of breast cancer cells." (PMID 31657716, 2019). "CARM1 is a protein that plays a role in the spread of breast cancer cells, and scientists are currently looking for a small molecule that will inhibit its action." (PMID 31657716, 2019). "In lymph-node-positive tumors, we found members of the CARM1 and regulation of the ER pathway (CARM_ER) to be enriched, potentially indicating an involvement of chromatin-remodeling factors in breast cancer progression and metastasis." (PMID 31315058, 2019). "To further evaluate 6a as a chemical probe against CARM1, we quantified the efficiency by which 6a engages CARM1 in a cellular context and thus suppresses the CARM1-dependent invasion by breast cancer cells." (PMID 31657716, 2019). "Our prior work showed that the methyltransferase activity of CARM1 is required for breast cancer metastasis." (PMID 31657716, 2019). "PKM2 can be methylated by CARM1 to reversibly shift the metabolism from OXPHOS to aerobic glycolysis in breast cancer cells." (PMID 30845728, 2019).
breast carcinoma (continued). "CARM1 has been found to be overexpressed in several cancer types such as breast cancer, colorectal cancer and prostate cancer, where it exhibits oncogenic properties." (PMID 31217904, 2019). "Our prior efforts using in vivo mouse and in vitro cell models uncovered the role of CARM1 in promoting breast cancer metastasis." (PMID 31657716, 2019). "We thus characterized SKI-73 (6a) as a chemical probe that can be used to interrogate the CARM1-dependent invasion of breast cancer cells." (PMID 31657716, 2019). "CARM1 has been shown to be overexpressed in several cancer types such as colon cancer, prostate cancer and breast cancer." (PMID 31217904, 2019). "Previous studies establish an oncogenic function of CARM1 in the context of colorectal and breast cancer, which correlate to its overexpressed condition." (PMID 31217904, 2019). "This methylation of BAF155 is associated with breast cancer recurrence and metastasis, indicating that CARM1 plays an important role in breast cancer progression through BAF155." (PMID 30150556, 2018). "Here the authors use quantitative mass spectrometry to globally profile the substrates of the PRMT CARM1 in breast cancer cells, and establish a role for CARM1's N-terminus in substrate recognition." (PMID 28537268, 2017). "Here we employed a quantitative mass spectrometry approach to globally profile CARM1 substrates in breast cancer cell lines." (PMID 28537268, 2017). "We discover three additional pathways viz., Glycerophospholipid metablism, h-Efp pathway and CARM1 and Regulation of Estrogen Receptor, which can be related to the metastasis phase of breast cancer." (PMID 28432361, 2017). "Carm1 was shown to be essential for estrogen-induced cell cycle progression in breast cancer cell lines." (PMID 27556302, 2016). "Several studies described an aberrant expression of Carm1 in hormone-dependent tumors, such as prostate and breast cancers, but also in other types of cancers." (PMID 27556302, 2016). "CARM1 plays opposing roles in proliferation and differentiation in breast cancer cells through the expression of two splice isoforms, CARM1FL and CARM1ΔE15." (PMID 26030442, 2015). "It has been reported previously that CARM1 is enriched in HER2+ breast cancer; however, the localization of CARM1 expression in the epithelial and stromal compartments was not described in that study." (PMID 26030442, 2015). "Recent studies, however, have shown that CARM1 expression correlates with poor prognosis, indicating a need for further studies of both CARM1 isoforms in a large cohort of breast cancer specimens." (PMID 26030442, 2015). "Recent studies suggest that CARM1 expression also correlates with specific sub-cellular compartments that vary by molecular subtype and with clinical outcomes in breast cancer patients." (PMID 26030442, 2015). "The authors then demonstrated that methylation of BAF155 at arginine residue R1064 affects the colony-formation capacity of MCF7 breast cancer cells and that this modification is entirely dependent on CARM1." (PMID 25927994, 2014). "In breast cancer, CARM1 has been recently shown to regulate estrogen dependent cell proliferation through upregulation of the transcription factor E2F1, an essential component of cell cycle regulation." (PMID 23663560, 2013). "Our results support the value of using CARM1 in prognostic stratification of breast cancer patients and its potential therapeutic implications in targeting treatment." (PMID 23915145, 2013). "The mRNA level of CARM1 was found to be elevated in grade 3 breast tumors in a cohort of 81 human breast carcinomas of various types." (PMID 23915145, 2013). "The strong correlation of the expression pattern of CARM1 and ERα in breast cancer cells implicates roles of CARM1 in ERα biology." (PMID 23723242, 2013).
breast carcinoma (continued). "Although the regulation of ERα-dependent transcription and biological effects by CARM1 has been studied extensively in breast cancer cells, the co-localization of CARM1 with ERα in primary breast tumors and normal mammary gland has not been well characterized." (PMID 23723242, 2013). "We investigated CARM1 levels and localization across breast cancer tumors in a cohort of patients of either European or African ancestry." (PMID 23663560, 2013). "While another study demonstrated there was inverse correlation between CARM1 expression and tumor grade in ER + and LN-breast cancer cases." (PMID 23915145, 2013). "Previous reports have shown that CARM1 plays an essential role in estrogen-mediated transcriptional activation, and is necessary for the estradiol (E2)-induced proliferation of breast cancer cells." (PMID 23915145, 2013). "One limitation of the study is that we didn’t know the relationship of CARM1 overexpression and the prognosis of breast cancer." (PMID 23915145, 2013). "In normal breast tissue, CARM1 regulates ERα-stimulated proliferation and differentiation, activities which are deregulated in breast cancer, with the balance shifting to enhanced ERα proliferative activity." (PMID 23723242, 2013). "CARM1 is an essential part of the estrogen-stimulated breast cancer growth downstream of ERα and its aberrant expression as well as PRMT1 overexpression is linked to breast cancer." (PMID 21814622, 2011). "High or low expression of CARM1 was observed in ovarian cancers (d-e), lymphomas (f-g), lung cancers (h-i), breast cancers (j-l), colorectal cancers (n-p), and prostate cancers (r-t)." (PMID 20462455, 2010). "P69 normal prostate cells and the human breast cancer cell line MDA-MB-231 were used to demonstrate the baseline expression of CARM1." (PMID 20462455, 2010). "CARM1 overexpression was noted in some hormone-dominated tumors such as breast cancer (27%) and ovarian cancer (17%), and in only 6% of prostate cancers." (PMID 20462455, 2010). "AIB1/SRC3, is an oncogene, amplified in breast, prostate, pancreatic, and other cancers and CARM1 is over-expressed in grade-3 breast cancer tumors." (PMID 19707557, 2009). "Several circRNAs identified in our analysis, including hsa_circRNA_104310 (ZDHHC4, AUC = 0.80), hsa_circRNA_404935 (ZBTB16, AUC = 0.882), hsa_circRNA_003641 (ATM, AUC = 0.876), and hsa_circRNA_102445 (CARM1, AUC = 0.812), demonstrated strong discriminatory power across breast cancer subtypes." (PMID 41516402, 2026). "Essentially, our engineered cell line represents avaluable tool for discovering CARM1-targeting therapeutics that couldenhance current breast cancer treatment strategies." (PMID 41453375, 2026). "Notably, CARM1 degrader-1 exhibited over 100-fold increased potency in suppressing CARM1-mediated methylation relative to TP-064, and achieved comparable inhibition of cancer cell migration at 20-fold lower concentrations in breast cancer cells." (PMID 41152553, 2025). "This indicates that CARM1 is essential for oestrogen/ERα‐induced transcriptional activation, breast cancer cell growth, and tumorigenesis, making CARM1 a potential drug target for ERα‐positive and endocrine‐resistant breast cancer." (PMID 39964832, 2025). "Additionally, SKI‐73 (6a) summarised the impact of CARM1 knockout on the invasion of breast cancer cells." (PMID 39964832, 2025). "To understand mechanistically how CARM1 might be regulating NGFR signaling we used an antibody and mass spectrometry approach to define the known CARM1 substrates in NSC11 GSCs—a method previously used to identify CARM1 substrates in human breast cancer cells." (PMID 40321217, 2025). "Moreover, datasets analysis from Oncomine showed that CARM1 expression was significantly related to many carcinomas, such as breast cancer, salivary gland carcinoma, lung cancer, and Burkitt’s lymphoma." (PMID 38476024, 2024). "CARM1 was upregulated in breast cancer samples and positively correlated with histological grade." (PMID 38476024, 2024).
breast carcinoma (continued). "Our data thereby suggested that CARM1-mediated GATAD2A methylation might serve as a potential druggable target in breast cancer." (PMID 38676947, 2024). "In conclusion, these data support our hypothesis that CARM1 promotes proliferation and migration in TNBC and that its upregulation is linked to breast cancer progression." (PMID 38476024, 2024). "Compared to the full-length variant, the truncated CARM1 lacking exon 15 (CARM1-V4/ΔE15) in specific cells exhibits different localization and activity, particularly in breast cancers." (PMID 38619752, 2024). "Next, we examined whether CARM1-madiated GATAD2A methylation is required for breast cancer cell growth and tumorigenesis." (PMID 38676947, 2024). "Among all cancer types, the role of CARM1 in breast cancer was most studied." (PMID 38676947, 2024). "Therefore, targeting CARM1 enzymatic activity or peptide mimics interfering CARM1-mediated GATAD2A/2B methylation will provide a new therapeutic avenue for treating breast cancer as well as other CARM1-dependent cancers." (PMID 38676947, 2024). "Studies have shown that the citrullination of H3R17 by PAD4 on the ER-regulated pS2 promoter caused a significant decrease in estrogen-induced gene expression in MCF-7 breast cancer cells by interfering with methylation events mediated by CARM1 (also known as PRMT4)." (PMID 36365233, 2022). "Therefore, CARM1 can promote the proliferation of ERα -positive breast cancer cells and tumor growth in mice in vivo." (PMID 35311114, 2022). "Studies show that CARM1 methylated MED12 can increase chemosensitivity of breast cancer cells." (PMID 33495408, 2021). "Through mediating methylated modification of BAF155 and PKM2, CARM1 could enhance breast cancer progression and metastasis." (PMID 33436008, 2021). "Methylation of BAF155 appears to have a significant regulatory role in breast cancer cell migration and metastasis, as increased methylation of BAF155 mediated by coactivator-associated arginine methyltransferase 1 (CARM1) is associated with poor survival and metastatic lung colonization in mice." (PMID 33143733, 2020). "Due to its critical role in estrogen/ERα-induced gene transcriptional activation, we tested whether CARM1 regulates ERα-positive breast cancer cell growth and tumorigenesis." (PMID 32206101, 2020). "To explore the feasibility of dissecting the CARM1-dependent, invasion-prone subset of MDA-MB-231 breast cancer cells, we formulated a cell-cycle-aware algorithm of scRNA-seq analysis and dissected those subpopulations that were sensitive to CARM1 perturbation." (PMID 31657716, 2019). "SKI-73 (6a) recapitulates the effect of CARM1 knockout against breast cancer cell invasion." (PMID 31657716, 2019). "High-level expression of CARM1 has been observed in several cancers, including those of prostate, colon, and breast, with levels higher in metastatic breast cancer than in primary breast cancer." (PMID 29983869, 2018). "CARM1 expression is dysregulated in colorectal, prostate and breast cancer." (PMID 30150556, 2018). "To investigate the functional roles and the prognosis potential of CARM1 alternative spliced isoforms in breast cancer, we used recently developed antibodies to detect differential CARM1 isoform expression in subcellular compartments and among malignant and benign breast tumors." (PMID 26030442, 2015). "Thus, further elucidation of the role of CARM1 in breast cancer will require experiments that also take into account functional differences between these two related, yet distinct players in human cancers." (PMID 26030442, 2015). "This study also demonstrates no obvious association of CARM1 isoform expression and clinical correlates in breast cancer." (PMID 26030442, 2015). "Given the roles of CARM1 splice isoforms in proliferation and differentiation in breast cancer cells as well as its clinical correlates, CARM1 may be a potential prognostic biomarker." (PMID 26030442, 2015).
breast carcinoma (continued). "In fact, CARM1 is required for ER dependent breast cancer cell differentiation and this suggests CARM1 may impact the ER status in breast cancer." (PMID 23663560, 2013). "Factors which facilitate the sub-cellular localization CARM1 may play a vital role in breast cancer subtype etiology." (PMID 23663560, 2013). "In summary, based on previous work and the results presented here, CARM1 may promote tumor cell growth by activating nuclear receptors and multiple growth factor signaling cascades in breast cancer." (PMID 23915145, 2013). "It still remains unknown the expression pattern of CARM1 in breast cancer and its relationships with clinicopathological characteristics and molecular subtypes." (PMID 23915145, 2013). "We also found that the rate of CARM1 expression was significantly different among different molecular subtypes of breast cancer, which may hint at a different mechanism and prognosis value." (PMID 23915145, 2013). "This suggests that CARM1 might have the potential to improve the stratification and personal management of patients suffering from breast cancer." (PMID 23915145, 2013). "All these reports suggest CARM1 is an important factor involved in progression and may affect prognostication of breast cancer." (PMID 23915145, 2013). "Furthermore, using a gain-of-function approach in ERα-positive breast cancer cells, we showed that 2-fold CARM1 overexpression in MCF7 cells led to growth inhibition, activation of differentiation markers and inhibition of anchorage-independent growth." (PMID 23723242, 2013). "In addition to histone methylation, CARM1 has been implicated in methylation of other proteins, including SRC-3 which indirectly impacts estrogen mediated breast cancer cell line proliferation." (PMID 23663560, 2013). "Cancers of the breast and prostate have been shown to overexpress CARM1." (PMID 20462455, 2010). "In support of this, we have found that iAs-mediated inhibition of an estrogen-responsive promoter in MCF7 breast cancer cells is functionally related to iAs effects on CARM1 and on SRC3/AIB1 a GRIP1 homologue that interacts with ERs (manuscript in preparation)." (PMID 19707557, 2009). "Furthermore, the distribution of CARM1 and CARM1-ΔE15 proteins differs in breast cancer cells." (PMID 38619752, 2024). "For example, in the most studied breast cancer, CARM1 could methylate the R838 site of lysine demethylase 1 (LSD1) to promote the binding of deubiquitinase USP7, resulting in the ubiquitination and stabilization of LSD1, thereby promoting the invasion and metastasis of breast cancer cells." (PMID 35033016, 2022). "Our data thereby revealed that CARM1 is required for estrogen/ERα-induced transcriptional activation, breast cancer cell growth and tumorigenesis, suggesting CARM1 might serve as a potential drug target in ERα-positive and endocrine therapy-resistant breast cancer." (PMID 32206101, 2020). "Therefore, developing small molecule inhibitors targeting CARM1 enzymatic activity or peptides mimicking sequence motifs in CARM1 methylation sites will provide an additional therapeutic adjunct for ERα-positive and endocrine therapy-resistance breast cancers." (PMID 32206101, 2020). "In addition to in vitro data that supports that CARM1 isoforms are important cancer related proteins, several previous studies have suggested that overall CARM1 expression is related to oncogenesis and poor outcomes in human breast cancer tissues." (PMID 26030442, 2015).